SLN (sarcolipin)
Description:
Reversibly inhibits the activity of ATP2A1/SERCA1 and ATP2A2/SERCA2 in sarcoplasmic reticulum by decreasing the apparent affinity of the ATPase for Ca(2+). Also inhibits the activity of ATP2A3/SERCA3 (By similarity). Modulates calcium re-uptake during muscle relaxation and plays an important role in calcium homeostasis in muscle. Required for muscle-based, non-shivering thermogenesis (By similarity).
Synonyms: MGC12301; MGC125854; MGC125855
Tractability: Antibody: UniProt predicts a signal peptide or a membrane-spanning region.
Gene: Protein-coding gene on chromosome 11 (107,707,375 to 107,719,696, reverse strand). Ensembl gene ENSG00000170290.
Subcellular location: Sarcoplasmic reticulum membrane; Endoplasmic reticulum membrane
Subcellular location (Human Protein Atlas): Microtubules
Pathways (Reactome):
Muscle contraction: Ion homeostasis
Transport of small molecules: Ion transport by P-type ATPases
Gene Ontology:
Molecular function: protein binding; ATPase binding; enzyme inhibitor activity; enzyme regulator activity
Biological process: negative regulation of ATPase-coupled calcium transmembrane transporter activity; regulation of ATPase-coupled calcium transmembrane transporter activity; calcium ion transport; negative regulation of calcium ion import; negative regulation of calcium ion import into sarcoplasmic reticulum; negative regulation of protein-containing complex disassembly; positive regulation of cold-induced thermogenesis; positive regulation of protein depolymerization; regulation of calcium ion transport; regulation of relaxation of muscle; sarcoplasmic reticulum calcium ion transport
Cellular component: sarcoplasmic reticulum; sarcoplasmic reticulum membrane; endoplasmic reticulum membrane; membrane
Genetic constraint (gnomAD): Loss-of-function variants: 0 observed, 1.28 expected, observed/expected ratio (o/e) 0, 90% interval 0 to 1.63. That is too few expected variants to judge how well the gene tolerates losing a copy. Missense variants: 33 observed, 37.13 expected, observed/expected ratio (o/e) 0.89, 90% interval 0.67 to 1.19. Synonymous variants: 18 observed, 14.53 expected, observed/expected ratio (o/e) 1.24, 90% interval 0.85 to 1.78.
Homologues: Orthologues: chimpanzee SLN (100% identical).
Diseases named in the same sentence as SLN in open-access papers:
SLN is named in the same sentence as 22 diseases in open-access papers, as found by Europe PMC text mining. Sharing a sentence is not in itself a finding about the gene and the disease. The quoted sentences say what the papers report.
Duchenne muscular dystrophy (4 papers, 2017 to 2023). Duchenne muscular dystrophy (DMD) is a neuromuscular disease characterized by rapidly progressive muscle weakness and wasting due to degeneration of skeletal, smooth and cardiac muscle. "Sarcolipin is abundantly expressed in Duchenne muscular dystrophy, and promotes an aging-associated muscle cell fibrosis." (PMID 34078750, 2021).
Obesity (4 papers, 2015 to 2023). Accumulation of substantial excess body fat. "It is reported that exercise-induced apelin in mothers activates sarcolipin and uncoupling protein 3 (UCP3) in the muscles of children and protects them from obesity because Sarcolipin and UCP3 regulate thermogenesis in muscles to improve metabolic homeostasis." (PMID 36093083, 2022). "Our finding of SLN downregulation in groups II and III matches in vivo evidence previously reported from SLN knockout mice and obese individuals, which may be driven by the obesity-induced alteration in SR phospholipid milieu." (PMID 35996069, 2022). "In a recent sarcolipin knockout (SLN−/−) study in mice, it was reported that sarcolipin was protective against hypothermia and obesity induced by a high fat diet; these effects were attributed to muscle-based thermogenesis, through the influence of sarcolipin on SERCA." (PMID 25660043, 2015).
takotsubo syndrome (3 papers, 2016 to 2022). "Calcium dysregulation has been demonstrated in stress cardiomyopathy, and increased densities of calcium-regulatory proteins, such as sarcolipin, have been found in cardiomyocytes of patients with stress cardiomyopathy." (PMID 27006838, 2016).
Arrhythmia (2 papers, 2015 to 2016). Any cardiac rhythm other than the normal sinus rhythm. "These electrical changes were coupled with altered cardiomyocyte calcium handling apparent in POAF atria prior to the onset of arrhythmia, as evidenced by changes in SLN, MYH6 and SERCA2a gene expression and reduced sarcolipin protein expression." (PMID 27390994, 2016). "Moreover, calcium handling and contractile function genes (SLN, ACTC1, PLCD4, PLCZ), potential arrhythmia-related genes (MYO5B, KCNA5), and cytoskeleton and cellular organization-related genes (XIRP2, COL8A1, KCNA6) were among the most deregulated genes in rTOF ventricles." (PMID 26252659, 2015).
cardiac hypertrophy (2 papers, 2011 to 2016). "In the heart, sarcolipin is regulated by mechanical stress and ablation of the sarcolipin gene results in cardiac hypertrophy." (PMID 22046435, 2011).
cardiomyopathy (2 papers, 2017 to 2022). A disease of the heart muscle or myocardium proper. "Sarcolipin, an inhibitor of sarco/endo plasmic reticulum Ca2+-ATPase (SERCA), was significantly upregulated in different types of muscular dystrophies, including LMNA-related cardiomyopathy, while downregulation of sarcolipin led to delays in cardiac dysfunction in a mouse model." (PMID 36555163, 2022).
disc degeneration (2 papers, 2018 to 2024). "The differential expression patterns of NLRP3, observed through comparative analysis of sham, vehicle-treated, and sLN-treated discs, underscore the potential of sLN as a modulator of inflammasome-mediated pathways in the context of disc degeneration." (PMID 39456246, 2024). "This detailed visual guide not only illustrates the complex interactions involved in sLN-mediated inhibition of inflammasome activation but also highlights the therapeutic potential of sLN in mitigating inflammation-driven disc degeneration, offering insights into future clinical applications." (PMID 39456246, 2024). "Thus, pharmacologically, sLN supplementation could be a novel therapeutic approach for treating disc degeneration." (PMID 30157962, 2018). "We hypothesize that sLN inhibits NLRP3 activation in NP cells through CD14 interaction, preventing disc degeneration progression." (PMID 39456246, 2024).
heart failure (2 papers, 2015 to 2018). Inability of the heart to pump blood at an adequate rate to meet tissue metabolic requirements. "While in rodents a decrease in SR calcium content is associated with reduced SERCA, PLB, and sarcolipin expression, a somewhat different story predominates in large mammals in which atrial SR calcium content increases in heart failure despite decreased calcium reuptake by SERCA." (PMID 30337881, 2018). "Sarcolipin protein expression was increased in the atrial myocardium of a dog model of pacing induced heart failure, whereas SLN protein level was decreased in atria of ischemic myocardium." (PMID 25671318, 2015). "However, other changes have been observed which would be expected to increase SERCA function in heart failure including an increase in phosphorylation of PLB at the CaMKII site and a decrease in sarcolipin levels." (PMID 30337881, 2018).
arthrogryposis (1 paper, 2022). A rare, non-progressive congenital disorder characterized by multiple joint contractures which are present at birth. "However, in the Angus cattle, although there were genes involved in inflammatory disease (OXT) and microcystic adenoma (SHISAL2B), the main function of DEGs was enriched in arthrogryposis (TNNT3 and TNNI2) and myopathy and myasthenic syndrome (MSTN, MYH2, and SLN)." (PMID 35495650, 2022).
chordoma (1 paper, 2025). Chordomas are rare malignant tumors arising from embryonic remnants of the notochord in axial skeleton. "The expression analysis identified significant downregulation of SPOCK3, NRK, MYH8, DLK1 and SLN, alongside upregulation of HLA-DQA1, GDA, CXCL11, CXCL9 and ADAMDEC1 in chordomas." (PMID 40386066, 2025).
Hypothermia (1 paper, 2017). Reduced body temperature due to failed thermoregulation. "Hypothermia induced by KD did not affect thermogenic genes such as Sarcolipin and Pgc1a in muscles and Ucp1 in adipose tissues." (PMID 28588221, 2017).
imbalance (1 paper, 2019). "Interestingly, many of the genes (such as sarcoplasmic reticulum Ca2 + -ATPases (SLN), Ras-related glycolysis inhibitor, and calcium channel regulator (Rrad), insulin receptor substrate 2 (irs2), and peptide transporter 2 (PEPT2)) are associated with metabolic imbalance and weight-related diseases." (PMID 31519904, 2019).
tumor (3 papers, 2019 to 2023). "The expression of several race-associated genes was also dependent on the MED12 mutation status of the tumor, being higher (FRAT2, TNFRSF19, ACP7, IRS4, PLEKHG4B, KRT17, SLN, and ZNF703) or lower (CAV2) in the mutated specimens compared with wild-type tumors." (PMID 37686244, 2023).
degenerative diseases (1 paper, 2024). "Finally, this study sets the stage for further investigations into the therapeutic potential of peptides like sLN in not only IVDD but also other inflammatory and degenerative diseases." (PMID 39456246, 2024).
SLN also shares sentences with these, for which no sentence is quoted: glioma (2 papers); myopathies (2); cancer (1); centronuclear myopathy (1); facioscapulohumeral muscular dystrophy (1); Insulin resistance (1); muscular dystrophies (1); prostate carcinoma (1).